RET (ret proto-oncogene)
Diseases named in the same sentence as RET in open-access papers (continued):
Sharing a sentence is not in itself a finding about the gene and the disease.
melanoma (continued). "The difference in Gfra1 and Gdnf transcript expression levels between benign tumors and malignant melanomas from RET-mice was statistically significant (p<0.05)." (PMID 20422010, 2010). "We previously demonstrated that cutaneous malignant melanomas develop in oncogenic RET (RFP-RET)-carrying transgenic mice." (PMID 20422010, 2010). "On the other hand, the present results showed that not only RFP-RET but also c-Ret, Gfra1 and Gdnf expression levels in malignant melanomas were definitely increased compared with those in benign melanocytic tumors in RET-mice." (PMID 20422010, 2010). "The difference between c-Ret transcript expression levels in benign tumors and malignant melanomas from RET-mice was statistically significant (p<0.05)." (PMID 20422010, 2010). "These dynamics of intrinsic c-Ret/Gfra1/Gdnf and introduced RFP-RET signaling in melanocytic tumors from RET-mice encourage us to examine the correlation between RET and human malignant melanoma." (PMID 20422010, 2010). "In other words, in triple-wild melanoma, it is necessary to investigate the otherwise very rare mutations/fusions, for which inhibitors (approved in other tumors) are available, such as those affecting NTRK1/3 genes or RET." (PMID 40361349, 2025). "Importantly, the plasma levels of 3HB, but not those of acetoacetate, negatively correlated with the size of RET melanomas." (PMID 33320838, 2021). "Since BGS treatment mediated RET melanoma cell death, we further examined whether tumor cell death was accompanied by an invasion of CD8+ cytotoxic cells into the tumor area." (PMID 34282238, 2021). "To confirm whether BGS would reduce the levels of extracellular Glu due to RET melanoma cell secretion, we examined CSF and plasma Glu concentrations in treated vs. untreated mice." (PMID 34282238, 2021). "Finally, we tested an immunosuppressive activity of tumor infiltrating PMN- and M-MDSC isolated from melanoma bearing RET transgenic mice." (PMID 33578808, 2021). "In order to examine whether BGS treatment, which can potentially shift Glu secreted by tumor cells from the brain to the blood, affects tumor growth, RET melanoma cells were injected into the right hemisphere." (PMID 34282238, 2021). "In the RET transgenic melanoma mouse model, sildenafil could also prolong mouse survival that was associated with reduced levels and activity of MDSC in the tumor microenvironment and, therefore, with a restored CD8+ T cell infiltration and function." (PMID 29942309, 2018). "Moreover, it was recently found that CCR5 is expressed on MDSC in RET transgenic melanoma-bearing mice and melanoma patients, playing an important role in their recruitment to the tumor microenvironment via the CCR5 ligands (CCL3, CCL4, and CCL5)." (PMID 29942309, 2018). "Here we showed that levels of Dtx3l/DTX3L in spontaneous melanoma in RFP/RET-transgenic mice and human melanoma cell lines were significantly higher than those in benign melanocytic cells and primarily cultured normal human epithelial melanocytes, respectively." (PMID 26033450, 2015). "Eight of 11 control mice (72.7 %) showed either retroperitoneal metastasis or mediastinal adenopathies, whereas only three of nine mice (33.3 %) in the HB-19-treated group showed visceral or lung metastasis: HB-19 treatment partly prevented metastasis of melanoma cells in RET mice." (PMID 24469254, 2014). "In a more relevant tumor model, we showed that HB-19 treatment for several months delays significantly the onset and frequency of spontaneous melanoma in RET mice, impairs tumor angiogenesis, and reduces metastasis while displaying no toxicity to normal tissue." (PMID 21812966, 2011). "We finally examined the physiological effect of GDNF stimulation on proliferation of HM3KO and G361 human malignant melanoma cells, which have no polymorphism at the G691S juxtamembrane region in c-RET as shown in a previous study." (PMID 20422010, 2010).
melanoma (continued). "In this study, we showed that expression levels of intrinsic c-Ret, glial cell line-derived neurotrophic factor (Gdnf) and Gdnf receptor alpha 1 (Gfra1) transcripts in malignant melanomas from RET-transgenic mice were significantly upregulated compared with those in benign melanocytic tumors." (PMID 20422010, 2010). "As for triple-wild melanoma, analysis with larger gene panels is worthwhile, as it has a higher probability to find targets for tumor-agnostic targeted therapies in this tumor type, such as RET, NTRK (neurotrophic tyrosine receptor kinase), ALK (anaplastic lymphoma kinase) or even IDH1 mutations." (PMID 40361349, 2025). "Besides, the highest proliferative index was found in RET melanoma metastases (76.7% ± 4.4)." (PMID 35109875, 2022). "Thus, we might have partially addressed the correlation between RET and malignant melanoma by integrating the previous and present results for mice and humans." (PMID 20422010, 2010). "SOX family members are common PAX protein co-factors; in melanocytes and melanoma, PAX3 interacts with SOX10 and drives a number of downstream genes, such as MITF, MET, and RET." (PMID 40428399, 2025). "In a RET.AAD (transgenic for the human oncogene RET and the mouse/human chimeric MHC antigen AAD), spontaneous melanoma mouse model, successful dissemination was observed as early as 3 weeks after primary tumor onset." (PMID 38426087, 2024). "In various cancers, including glioblastoma, melanoma, breast, lung, and prostate, tyrosine kinases are the most representative of these kinases, e.g., ALK, ROS1, RET, and FGFR." (PMID 35054873, 2022). "High and intermediate metastatic melanoma cell lines (WT31, B16F10 luc2 and RET) (HIM-melanoma) were therefore compared to the ones with low metastatic efficiency (D4M or HCmel12) (LM-melanoma)." (PMID 35109875, 2022). "The effect of CXCR2 inhibition on PMN-MDSC migration and tumor progression was studied in RET transgenic mice and in C57BL/6 mice after surgical resection of primary melanomas." (PMID 33578808, 2021). "Using the RET transgenic mouse melanoma model that shows similarity to human melanoma, we demonstrated previously a critical role of MDSC in melanoma progression." (PMID 33578808, 2021). "Rearrangements in several genes, including BRAF, RET, ROS1, ALK, NTRK1, and NTRK3, have been characterized in subsets of melanoma." (PMID 32123303, 2020). "Retrospective studies of spitzoid neoplasms have found activating fusions involving BRAF, RET, ROS1, ALK, or NTRK1 in 39% of melanomas with spitzoid morphology and just over 50% of Spitz nevi and atypical Spitz tumors." (PMID 32123303, 2020). "In the old situation within specialised hospitals, we assumed that multiple single-gene tests were performed, minimally three for NSCLC patients (a multigene panel, HER2/EGFR, and ALK, ROS, RET, or MET) and two for melanoma patients (BRAF and NRAS or KIT)." (PMID 27899957, 2016). "Results of our previous study using RET-mice also showed that levels of protein expression and activity of RFP-RET in malignant melanoma were increased compared with those in benign melanocytic tumors." (PMID 20422010, 2010). "In neural crest, melanocyte, and melanoma cells, PAX3 was found to regulate MITF, NGN2, RET, SOSTDC1, MSX2, DCT, and TYRP1 genes, as well as genes expressed ubiquitously or widely (and including melanocytes), such as BCL-XL, CXCR4, FGFR4, HES1, MET, NF1, TGFb2, and WNT1." (PMID 40428399, 2025). "Fusion genes in solid tumors may also occur, but in the case of melanoma these are very rare, affecting BRAF, ROS1, RET or NTRK." (PMID 36980598, 2023). "In addition, the genes EBI3, GH1, SOX9, RET, and SPRY2 are also good candidates for HH-GLI targets but exhibited a less uniform expression pattern in these melanoma cell lines." (PMID 36139698, 2022). "In addition, increased intratumoral CXCL1 level in RET transgenic mice, in contrast to CXCL5, significantly correlated with the accumulation of melanoma infiltrating PMN-MDSC." (PMID 33578808, 2021).
melanoma (continued). "Moreover, RET melanoma cells were detected inside macrophages, as was demonstrated by co-localization of CD68 macrophage and mCherry RET cells with fragmented condensed nuclei." (PMID 34282238, 2021). "Furthermore, RET melanoma cells surrounded by CD8+ cells expressed a high level of p-STAT1, which was significantly increased within melanoma cells in the BGS-treated group." (PMID 34282238, 2021). "Using the RET transgenic mouse model of malignant melanoma, it was demonstrated that ultra-low non-cytotoxic doses of paclitaxel induced a reduction of MDSC numbers and immunosuppressive activity, resulting in an increased survival of melanoma-bearing mice." (PMID 29942309, 2018). "Although Ret kinase mutations have not been found in human melanomas, the RET oncogene stimulates the downstream MAP kinase pathways, which are typical of melanoma and may explain melanoma formation, in the transgenic mice." (PMID 28229253, 2017). "TCGA analysis detected fusions in BRAF and RAF1 kinases in melanomas, but did not report fusions in ALK, ROS1, MET, RET, or NTRK, which are clinically targetable." (PMID 34831002, 2021). "Additionally, lenvatinib’s secondary antitumor effect is its direct melanoma cytotoxicity, which was not VEGFR-2 dependent and alternatively could be due to effects on FGFRs, PDGFRα, KIT, or RET." (PMID 36821392, 2023).
thyroid (58 papers, 2000 to 2026). "This study aimed to verify the prevalence of mutations in the BRAF, and RAS genes, and RET/PTC rearrangements in patients undergoing fine-needle aspiration biopsy (FNAB) for thyroid nodule evaluation in a real-world public health service population." (PMID 40748901, 2025). "It seems that RET/PTC is a leading mutation in thyroid carcinogenesis, it is especially related to the classic PTC subtype." (PMID 36605433, 2022). "RET mutations and rearrangements now represent a well-established mechanism that drives tumor growth across several types of neoplasms, including thyroid and lung cancer." (PMID 33806299, 2021). "Thyroid nodule investigation was the most common presentation (79%), although two patients were identified following familial RET mutation screening and were ultimately found to have a diagnosis of MTC." (PMID 25487826, 2015). "A change from allele G to allele A of rs1799939 may activate RET via leading to an amino acid change from glycine to serine, which played a vital role in thyroid carcinogenesis." (PMID 34950210, 2021). "Moreover, we recently showed that the loss of one or two alleles of the Patz1 gene enhances thyroid carcinogenesis in mice transgenic for the RET/PTC1 oncogene." (PMID 30744101, 2019). "Vandetanib, a critical therapy for advanced thyroid and RET-driven cancers, is limited by life-threatening hepato-cardiotoxicity." (PMID 41694587, 2026). "The discovery of the RET proto-oncogene and its association with cancer has led to the development of highly specific RET inhibitors, which have transformed the therapeutic landscape for RET-altered cancers, including thyroid and NSCLCs." (PMID 39655713, 2025). "Selpercatinib (RETEVMOTM) and pralsetinib (GAVRETOTM) are highly selective RET inhibitors designed to overcome the gatekeeper mutations and approved by the FDA in 2020 for RET-mutant thyroid and lung cancers." (PMID 38378752, 2024). "Selpercatinib (LOXO-292) is the first RET-specific kinase inhibitor approved by the FDA to treat RET-altered thyroid and NSCLC tumors." (PMID 39777333, 2024). "In Japan pathologists agreed that “relevant genomic biomarker tests for RET-altered lung (32%) and thyroid (23%) cancer are available in their clinical setting,” compared to 63% and 75% in the UK, 95% and 90% in Germany and 77% and 87% in the US (p = < 0.001)." (PMID 37277734, 2023). "It has been widely demonstrated that BRAF and RAS mutations, RET/PTC rearrangements, and also ALK mutations activate MAPK pathway, which has a key role in thyroid tumorigenesis." (PMID 32982967, 2020). "Four molecular alterations, BRAF and RAS point mutations, and RET/PTC and PAX8/PPARγ rearrangements, are the most frequent causes of thyroid papillary and follicular carcinomas." (PMID 29721199, 2018). "CCDC6 gene is often found rearranged to RET and to genes other that RET in thyroid and non-thyroid human neoplastic diseases." (PMID 22655027, 2012). "In recent years, extensive research on the RET/PTC signaling pathway has greatly advanced our understanding of the mechanisms of thyroid tumorigenesis." (PMID 18498667, 2008). "Activation of the RET gene at its chromosomal locus occurs in from about 20% to more than 40% of sporadic PTCs, including micro-carcinomas, and is thus an early event in thyroid carcinogenesis." (PMID 17667921, 2007). "miR-146b-5p positively regulates migration and invasion of thyroid normal and tumor follicular cells (independently from their original mutation, either BRAF or RET/PTC), through a mechanism that involves the actin cytoskeleton but not an increased capacity of matrix degradation." (PMID 26883911, 2016).
thyroid (continued). "Our data on OGG1 protein expression suggest that it was physiologically regulated in response to oxidative modulation of ErbB, and that these might be dysregulated in the signaling pathway involving AKT in the progression of thyroid malignancies with RET/PTC rearrangements." (PMID 35269445, 2022). "However, our data on Patz1+/− mice that do not express RET/PTC1 in thyroid cells suggest that PATZ1 downregulation could be itself an initial event of thyroid carcinogenesis, independently from RET/PTC1." (PMID 29584698, 2018). "The RET (rearranged during transfection) proto-oncogene has attracted much interest in DTC because aberrant activation of RET by somatic rearrangements or point mutations is a unique genetic event in DTC, which also plays a significant role in thyroid carcinogenesis." (PMID 29131865, 2017). "Although PTC is the most common thyroid malignancy in both pediatric and adult populations, established molecular differences—such as the predominance of BRAFV600E and RAS mutations in adults versus RET, NTRK, ALK, and MET alterations in children—may result in cytomorphological differences." (PMID 41462793, 2025). "We also evaluated alkynyl nicotinamide RET TKIs in KIF5B-RET-induced lung tumors in immune competent transgenic mice, and in CCDC6-RET fusion-positive thyroid patient-derived xenograft PDX.003.047 tumors." (PMID 40496186, 2025). "Additional cytogenetic events such as RET amplifications have been described in MTC, PTC, and anaplastic thyroid cancer, although their role in thyroid carcinogenesis remains questionable." (PMID 37627175, 2023). "In thyroid cancer, point mutations in Ras and BRAF genes, as well as rearrangements of the RET gene (RET/PTC), lead to the constitutive activation of MAPK pathways that initiate and/or sustain thyroid tumorigenesis." (PMID 29467389, 2018). "In the early phases of thyroid oncogenesis, BRAF p.V600E or RET/PTC oncogenes drive the expression of HIF1α, although the concomitant overexpression of c-MYC, belonging to the same signaling pathway, quickly overturns HIF1α regulation by suppressing BGLT3 transcription at its locus." (PMID 41489907, 2026). "Thyroid disease in the patient’s family, Hashimoto’s disease, and hypothyroidism, as well as the type of thyroidectomy, the need for indicating RAI, and smaller tumor size, clustered quite well with gene fusions related to RET, CCDC6, MET, EML4, and ALK." (PMID 39409115, 2024). "Since the publication of the tumor-agnostic cohort of LIBRETTO-001, additional case reports of activity in non-NSCLC and non-thyroid RET-altered cancers have emerged, including in tumor types which were not previously represented in the LIBRETTO-001 data set." (PMID 37627175, 2023). "Previously, H2O2 was reported to cause RET/PTC1 rearrangement (a signature of radiation-induced PTC) in thyroid cells, suggesting that oxidative stress contributes to RET/PTC1 formation found in thyroid lesions, even in the absence of radiation exposure." (PMID 37891977, 2023). "Then, in order to validate the tumor suppressor role of PATZ1 in thyroid carcinogenesis in vivo, we crossed a mouse model of PTC, carrying the RET/PTC1 oncogene under the thyroid-specific control of the bovine thyroglobulin promoter with mice knockout for the Patz1 gene." (PMID 29584698, 2018). "Interestingly, evidence has been provided showing that rearranged during transfection/papillary thyroid carcinoma (RET/PTC) oncogene is induced by estrogen in breast cancer cells, and the RET/PTC kinase signaling enhances estrogen-driven cell proliferation." (PMID 28588554, 2017).
thyroid (continued). "We developed two complementary in vitro models based on RET/PTC1 oncogene, starting from the hypothesis that miRNAs modulated by a driving PTC-oncogene are likely to have a role in thyroid neoplastic processes." (PMID 24810336, 2014). "Supposed mechanisms include destructive thyroiditis, prevention of VEGF binding to normal thyroid cells and/or impairing thyroid blood flow, reduced synthesis of thyroid hormones, inhibition of iodine uptake, RET impairment, and progressive damage to thyroid function." (PMID 33105621, 2020). "Although the single mutational testing for BRAFV600E has high specificity for thyroid malignancy, the 2015 ATA guidelines do not recommended the systematic use of the single molecular status of BRAF; and a mutational panels (RAS, BRAF, RET/PTC.)." (PMID 34394248, 2020).